MYC (MYC proto-oncogene, bHLH transcription factor)
Diseases named in the same sentence as MYC in open-access papers (continued):
Sharing a sentence is not in itself a finding about the gene and the disease.
pancreatic cancer (397 papers, 1998 to 2026). "A previous study in pancreatic cancer showed that resistance to trametinib was associated with increased autophagy and reduced MYC activity." (PMID 40499006, 2025). "MYC depletion in murine pancreatic cancer caused an increase in γ‐H2AX signal in actively replicating cells and was associated with sensitization to ATR inhibition in the induction of DNA damage." (PMID 40488968, 2025). "MYC amplification, which is associated with poor prognosis and metastasis in pancreatic cancer, frequently co-occurs with WWP1 amplification." (PMID 39656237, 2025). "The association between the expression of CNOT2 and MYC and the characteristics of pancreatic tumors was confirmed using TCGA analysis." (PMID 37550432, 2023). "Loss of function of KDM6A causes squamous-like metastatic pancreatic cancer through aberrant activation of super-enhancers at the loci of MYC and RUNX3 oncogenes and consequent MYC and RUNX3 over-expression." (PMID 38135679, 2023). "The small GTPase KRAS is frequently mutated in pancreatic cancer and its cooperation with the transcription factor MYC is essential for malignant transformation." (PMID 36581205, 2022). "To unbiasedly find MYC-associated epigenetic dependencies, we conducted a drug screen in pancreatic cancer cell lines." (PMID 35439169, 2022). "In mouse models, KDM6A loss induces squamous-like metastatic pancreatic cancer through aberrant activation of super-enhancers that regulate ΔNp63, c-MYC and RUNX." (PMID 33669845, 2021). "Results revealed that low expression of FXN (frataxin) and high expression of MYC were associated with advanced grades of pancreatic tumors." (PMID 34711879, 2021). "Within those significant CNAs, we found that MYC amplification is the only variant across two different cancer types: metastatic prostate and pancreas cancers, suggesting its common role in promoting cancer metastasis." (PMID 34795255, 2021). "Aberrant MYC activities induce the dysregulated expression of a chemokine‐encoding gene cluster, therefore chemoattracting mast cells into the islets of pancreatic cancer." (PMID 32175651, 2020). "The tag SNP on 8q24.21 is located ~28 kb upstream of MYC at an established bladder cancer risk locus that is ~850 kb upstream of our previously reported pancreatic cancer susceptibility locus." (PMID 27579533, 2016). "The scientific literature reports that the amplification of the 8q24 locus involves the MYC oncogene, whose amplification is significantly associated with poor outcome in the adenosquamous subtype of pancreatic carcinoma and in cervical dysplasia." (PMID 27566563, 2016). "We speculate that drugs targeting the MYC-RUVBL1 axis could make pancreatic tumours susceptible to immunotherapy." (PMID 38821858, 2024). "Furthermore, we investigated the association between tiRNA, FUBP1, and c-MYC using tumor samples obtained from 12 pancreatic cancer patients." (PMID 38443680, 2024). "MYC mutations have been reported in pancreatic cancer and chronic pancreatitis." (PMID 36769322, 2023). "We conducted a correlation analysis to investigate whether iron homeostasis genes, FXN and MYC, are also associated with ferritin in contributing pancreatic cancer progression." (PMID 34711879, 2021). "FURIN and MYC were positively associated with healthy tissues and pancreatic cancer." (PMID 33796097, 2021).
pancreatic cancer (continued). "In particular, MYC gene expression was significantly higher in G3 pancreatic tumors compared to any other grades of pancreatic cancer, suggesting that elevated levels of MYC may contribute to the mechanisms underlying ferritin and increased risks of pancreatic cancer." (PMID 34711879, 2021). "Taken together, we present compelling evidence that the MYC-mRNA drug is effective as a monotherapy in in vitro and in vivo pancreatic cancer models using immunocompromised NSG mice." (PMID 40949131, 2025). "Another study demonstrated that MYC eRNA cooperates with YEATS2 to recruit the ATAC–HAT complex, thus enhancing MYC transcription in pancreatic cancer." (PMID 40761481, 2025). "Approximately 43.1%–74.7% of the primary and metastatic drug-resistant pancreatic cancers express MYC." (PMID 40949131, 2025). "The deletion of TBK1 in tumor cells reverts the survival benefit after depletion of MYC in a model of pancreatic cancer." (PMID 40488968, 2025). "GEM treatment induces MUC5AC overexpression in pancreatic cancer, disrupting E-cadherin/β-catenin junctions and promoting β-catenin nuclear translocation, which increases MYC expression." (PMID 39990228, 2025). "Previous studies have shown that reducing MYC levels in pancreatic cancer decreases GEM-induced neuroendocrine marker expression, increasing chemosensitivity." (PMID 39990228, 2025). "Here we show that a novel MYC eRNA regulates MYC gene expression during chronic inflammatory conditions in pancreatic cancer cells." (PMID 40216980, 2025). "Here, we report the in vivo downregulation and inhibition of metastatic c-MYC-expressing lethal pancreatic cancer by the mRNA drug 3′UTRMYC1-18." (PMID 40949131, 2025). "The c-MYC protein is an oncogenic transcription factor that regulates at least 15% of proliferation, differentiation, and metabolism-related genes in pancreatic cancer cells." (PMID 40100307, 2025). "Combined chemotherapy with niclosamide and gemcitabine induced β-catenin ubiquitination, consequently downregulated the β-catenin-c-MYC signaling pathway to inhibit pancreatic cancer progression." (PMID 40083702, 2025). "In pancreatic cancer, decreased levelsof PCNA were linked with alterations in the NRF2 pathway, while alterationsin the MYC/MYCN and HIPPO pathways was linked with increased PCNAlevels in lung and pancreatic cancer." (PMID 40657100, 2025). "TNF-α induced Tyrosine dephosphorylation of the YEATS domain increases MYC eRNA binding to the YEATS2 protein in pancreatic cancer cells." (PMID 40216980, 2025). "With this study, we have shown that the 3′UTRMYC1-18 drug is therapeutically effective both in vitro and in vivo in a titratable dose-dependent manner compared to the standard-of-care drugs in various MYC-driven lethal pancreatic cancers." (PMID 40949131, 2025). "The c-MYC oncogene has been shown to be overexpressed in primary (43.1%) and metastatic (31.6%) pancreatic cancers, respectively, and is the primary driver of the neoplastic changes and progression of pancreatic cancer metastasis." (PMID 40949131, 2025). "Taken together, these data demonstrate that the c-MYC-mRNA drug achieved dose-dependent, on-target inhibition of the lethal pancreatic tumors via dose-dependent downregulation of the c-MYC and PD-L1 expression." (PMID 40949131, 2025). "We demonstrated that lethal pancreatic cancer driven by c-MYC can be inhibited with the c-MYC-mRNA drug, 3′UTRMYC1-18, in a dose-dependent, titratable manner to achieve a remarkably significant survival outcome." (PMID 40949131, 2025).
pancreatic cancer (continued). "A well-studied BET protein-selective inhibitor that has been demonstrated to prevent pancreatic cancer development by inhibiting the expression of c-MYC, FOSL, and HMGA2." (PMID 40100307, 2025). "We transfected these siRNAs into MIA PaCa-2 pancreatic carcinoma cells (KRASG12C/WT) to identify the most potent based on reduced MYC mRNA and protein expression." (PMID 40762837, 2025). "To evaluate the potential impact of FUBP1 on c-MYC transcription in pancreatic cancer cells, we performed ChIP assays using specific antibody against FUBP1." (PMID 38443680, 2024). "Second, overexpression of the MYC oncogene promotes the progression of Kras-driven PanIN to PDAC in a mouse model of pancreas cancer, and MYC cooperates with SREBPs to control lipogenesis across a number of MYC-dependent cancers." (PMID 39240063, 2024). "RUVBL1 depletion mimicked cellular phenotypes previously observed on MYC depletion in pancreatic cancer cells." (PMID 38821858, 2024). "Here, the authors report that ZDHHC20-mediated S-Palmitoylation of the m6A reader YTHDF3 stabilizes MYC mRNA to promote the progression of KRAS-mutant pancreatic cancer." (PMID 38821916, 2024). "Taken together, our results reveal that m6A modifications in the MYC CRD are required for YTHDF3-mediated stabilization of MYC mRNA in pancreatic cancer." (PMID 38821916, 2024). "We subsequently validated through rescue experiments that PVT1 can promote the proliferation and migration of pancreatic cancer cells via MYC." (PMID 39376555, 2024). "We concluded that RUVBL1 and MYC co-occupy thousands of promoters in pancreatic cancer cells and that depletion or inhibition of RUVBL1 leads to their downregulation." (PMID 38821858, 2024). "We further observed a reduction in c-MYC expression levels in FUBP1-knockdown pancreatic cancer cells." (PMID 38443680, 2024). "This activation prompts the transcription of target genes, including MYC and Cyclin D1, which are pivotal for fostering uncontrolled cell proliferation and survival in pancreatic cancer." (PMID 39087024, 2024). "Overall, we concluded that high MYC expression renders pancreatic cancer cells dependent on RUVBL1/2 and that inhibition of the RUVBL1/2 complex is therapeutic at doses tolerated by healthy tissues." (PMID 38821858, 2024). "This complex modulates the m6A modification at the 5' end of c-MYC mRNA and the coding DNA sequence region (near the 5'UTR), thus regulating c-MYC expression and advancing the progression of pancreatic cancer." (PMID 39155349, 2024). "We concluded that RUVBL1 depletion in pancreatic tumours induces immune cell infiltration and therefore phenocopies the genetic silencing of MYC in similar tumour models." (PMID 38821858, 2024). "Since MYC promotes immune evasion in pancreatic tumours, 35 51 we analysed immune cell infiltration on RUVBL1 depletion and observed a rampant increase in CD3-positive cells within tumours on auxin treatment." (PMID 38821858, 2024). "A study reported that triptolide is able to inhibit the production of HIF1‐α as well as c‐MYC protein in pancreatic cancer cells." (PMID 38690008, 2024). "According to some reports, MYC is required for mutant-KRAS-driven tumor initiation and progression, and MYC inhibition has been demonstrated to impair the growth of pancreatic cancer." (PMID 39457457, 2024). "Recently, it was confirmed that translational regulation by HIF1 alpha and MYC ultimately regulates glycolysis in pancreatic cancer." (PMID 37737908, 2023). "JQ1 suppresses cell proliferation through several signaling pathways such as TNFA_Signaling_via_nfkb, L2_STAT5_SIGNALING, MYC signaling as well as multiple inflammatory transcriptional programs in pancreatic cancer." (PMID 37719017, 2023). "MYC plays a vital role as a master cell proliferation regulator in pancreatic cancer transformation and progression." (PMID 36769322, 2023).
pancreatic cancer (continued). "MYC has been linked to histological transdifferentiation in SCLC and pancreatic cancer, suggesting a role in tumor lineage plasticity." (PMID 38093367, 2023). "Recent bioinformatics study has demonstrated that E2F targets and MYC targets V1, which are the number of cell proliferation-related pathways, can serve as the predictive biomarker for pancreatic cancer." (PMID 37333498, 2023). "An adenoviral vector has been also used for the coexpression of tumor suppressor genes in pancreatic cancer cells leading to proliferation inhibition and reduced MYC phosphorylation." (PMID 36969025, 2023). "Autocrine IGF1 signalling has recently been identified as an essential survival mechanism for quiescent cancer cells derived from murine pancreatic tumours, allowing for growth and apoptosis resistance in spite of mutations in KRAS or MYC." (PMID 37608096, 2023). "This led to the identification of the compound UNC10112785 inhibiting CDK9, a protein kinase enhancing MYC protein stability by phosphorylating serine 62 in MBI, whereby substantial MYC destabilization was observed in pancreatic cancer cells." (PMID 36969025, 2023). "In pancreatic cancer, approximately 30% of tumors carry a de novo acquired, pancreatic-cancer-specific super-enhancer with marked H3K27 acetylation located near the 3′ region of MYC." (PMID 37443779, 2023). "Numerous studies showed a causal relationship with expression of oncogene c-MYC and BRD4, including pancreatic cancer." (PMID 37659057, 2023). "Tumor growth in pancreatic cancer is accelerated by MYC activation owing to the swift recruitment of mast cells to the tumor site." (PMID 37256127, 2023). "Inhibition of CDK4/6 and lysosome function overcomes c-MYC–mediated cell cycle entry in the face of trametinib and chloroquine co-treatment in pancreatic cancer." (PMID 36719686, 2023). "Data from GEPIA2 showed that PLK1 expression was positively correlated with MYC in lung and pancreatic cancer." (PMID 38104151, 2023). "Using patient-derived xenografts of KRAS- and MYC-driven pancreatic carcinoma, we show that coinhibition of topoisomerase 1 (TOP1) and bromodomain-containing protein 4 (BRD4) synergistically induces tumor regression by targeting promoter pause release." (PMID 37831776, 2023). "By screening for common oncogenes and suppressor genes, endothelium KRAS- and MYC-positive genes were enhanced in pancreatic cancer expression." (PMID 35755820, 2022). "Mechanistically, KRAS inhibits IFN gene expression via regulation of the oncogene MYC, which is consistent with previous observations in pancreatic cancer." (PMID 35857848, 2022). "Cumulatively, LINC01420 facilitates progression of pancreatic cancer via releasing MYC from inhibitory effects of miR-494-3p in cytoplasm and enhancing nuclear levels of MYC-activated KRAS." (PMID 35139853, 2022). "Mechanisms responsible for immune evasion of MYC-expressing tumour are starting to emerge with the observation that MYC prevented loading of dsRNA to TLR3 in pancreatic cancer cells, reducing NFκB signalling and MHC-I expression." (PMID 35343573, 2022). "Part of these genes have been reported in basic studies of pancreatic cancer and are closely related to the invasion and metastasis of pancreatic cancer according to the literature, including MYC, CDH2, SNAI1, YAP1, SOX2." (PMID 35237592, 2022). "A cooperative effect of KRAS mutation and the expression of c-MYC for invasion, as also observed in HCC44 cells in our model, and for immune modulation has been shown previously in animal studies for lung and pancreatic cancer." (PMID 35565305, 2022). "PRMT5 epigenetically regulated the expression of FBXW7, contributing to elevated c-MYC levels and subsequently enhanced glycolysis and proliferation of pancreatic cancer cells." (PMID 35515121, 2022). "Dose-dependent effects of the PPRHs were further examined in PC-3 and the MYC-regulation-sensitive AsPc-1 pancreatic cancer cell line." (PMID 36613820, 2022).
pancreatic cancer (continued). "YAP1 maintained the expression of MYC, whereas knockout of YAP1 caused considerable downregulation of MYC that resulted in growth arrest of pancreatic cancer cells and apoptosis." (PMID 34178644, 2021). "It is particularly gratifying to us to see that c-MYC is now being included in the list of the most commonly altered genes in the genetic progression model of pancreatic cancer." (PMID 34491463, 2021). "Our team also developed a pancreatic cancer model with a targeted expression of the c-MYC oncogene in pancreatic progenitors under the control of the tetracycline-responsive transactivator." (PMID 34491463, 2021). "Utilizing hallmark gene sets, MYC-related pathways and other pathways are enriched, which is consistent with previous studies where MYC has been reported to play a role in cell growth, proliferation, and tumorigenesis in pancreatic cancer." (PMID 33901011, 2021). "Similar to the mutant KRAS models, the survival of pancreatic cancer cells at primary and metastatic sites was dependent on the perpetual expression of c-MYC." (PMID 34491463, 2021). "The applicability of c-MYC as a marker for a dismal prognosis of pancreatic cancer has also been validated and can be attributed, in part, to elevated expression of this transcription factor in the basal subtype of PDAC that lacks GATA6." (PMID 34491463, 2021). "Another study has also shown that the dysregulated XLOC_006390/c-MYC axis increases glutamate metabolism and promotes the progression of pancreatic cancer to a higher stage." (PMID 34992497, 2021). "The IGF1/IGF-1R signaling axis was also shown to promote the survival of dormant pancreatic cancer cells after oncogenic KRAS or MYC ablation in pancreatic cancer cells." (PMID 33807785, 2021). "As previously documented, OLR1 triggered c-MYC upregulation to accelerate pancreatic cancer metastasis." (PMID 34921134, 2021). "Several recent publications have provided mechanistic insight into the significance of c-MYC as an essential downstream node of RAS signaling in pancreatic cancer and other malignancies." (PMID 34491463, 2021). "DCLK1 has previously been linked to the pro-oncogenic CSC markers c-MET and c-MYC, and gene set enrichment analysis demonstrated that DCLK1-IN-1 affected MET-driven oncogenesis in patient-derived pancreatic cancer organoids." (PMID 34830884, 2021). "In this study, we found that eIF4A1 overexpression rescued the diminished EMT and metastasis capabilities of c-MYC knockdown pancreatic cancer cells in vitro and in vivo." (PMID 34906136, 2021). "Here, we present a novel strategy for inhibiting EMT and metastasis in pancreatic cancer cells via c-MYC/miR-9 signaling." (PMID 34906136, 2021). "Before exploring the role of eIF4A1 and c-MYC in the regulatory effect in pancreatic cells, we analyzed eIF4A1 expression in the pancreatic cancer cell lines Panc-1, Capan-2, AsPC-1, and MiaPaca-2, and in the normal pancreatic ductal epithelial cell line HPDE." (PMID 34906136, 2021). "Expression regulation and pharmacological inhibition of eIF4A1 and c-MYC were performed to determine their role in migration, invasion, and metastasis in pancreatic cancer cells in vitro and in vivo." (PMID 34906136, 2021). "Treatment with the eIF4A1 inhibitor rocaglamide (RocA) or the c-MYC inhibitor Mycro3 either alone or in combination significantly decreased the expression level of EMT markers in pancreatic cancer cells in vitro." (PMID 34906136, 2021). "In consistent with the pancreatic cancer study, the transcriptomic and downstream analyses underscore the importance of mast cell in MYC activation in early‐stage LUAD." (PMID 32175651, 2020). "TPL induced downregulation of MYC in a dose-dependent manner in multiple pancreatic tumor cell lines that we tested, suggesting that it is one of the major targets of triptolide." (PMID 33168807, 2020).